TLR4 (toll like receptor 4)
Diseases named in the same sentence as TLR4 in open-access papers (continued):
Sharing a sentence is not in itself a finding about the gene and the disease.
Glucose intolerance (27 papers, 2013 to 2025). Glucose intolerance (GI) can be defined as dysglycemia that comprises both prediabetes and diabetes. "Our IPGTT experiments showed that global TLR4 deficient mice (Tlr4LoxTB) following chronic alcohol-containing liquid diet feeding developed systemic glucose intolerance." (PMID 36979389, 2023). "In contrast, when hepatic TLR4 was reactivated in mice (Tlr4LoxTB × Alb-Cre), alcohol feeding caused glucose intolerance in these mice compared with littermate controls (Tlr4LoxTB)." (PMID 36979389, 2023). "This was consistent with the observation that TLR4 deficiency protects the animals from glucose intolerance induced by HFD." (PMID 28898202, 2017). "This is also supported by the fact that TLR4 deficient mice are resistant to the induction of glucose intolerance through a high-fat diet (HFD)." (PMID 24369539, 2013). "The development of early NASH and glucose intolerance was significantly attenuated in FFC + S–fed mice compared to FFC-fed mice associated with lower hepatic toll-like receptor-4 mRNA expression, while markers of intestinal barrier function were significantly higher than in C-fed mice." (PMID 33809593, 2021). "The deletion of TNFR1 and TLR4 protected mice from higher fasting blood glucose and glucose intolerance, both observed in WT mice exposed to 1,2-NQ." (PMID 37383489, 2023). "Our data showed that reactivation of hepatocyte TLR4 exacerbated alcohol-induced glucose intolerance and decreased insulin signaling." (PMID 36979389, 2023). "In the liver, ingestion of bioactive food significantly increased antioxidant enzymes, decreased lipogenesis, reduced inflammation mediated by the TLR4-TNFα pathway along with a decrease in body fat, glucose intolerance, and metabolic inflexibility." (PMID 35010897, 2021). "Inflammation, specifically due to cytokines and chemokines produced by FFA and gut-derived LPS activation of TLR4 signaling, leads to systemic glucose intolerance by impairing insulin signaling in target tissues including adipose and liver." (PMID 29666152, 2018). "To examine the role of STAT3 and TLR4 in the development of glucose intolerance, we tested IL-6-induced insulin-stimulated uptake of 2-NBDG in the skeletal muscle." (PMID 28706484, 2017). "This indicates that the phenotype of TLR4, including Kupffer cells which are the predominant TLR4 expressing cells in the liver, plays a role in development of glucose intolerance." (PMID 26317345, 2015). "TLR4 deletion protected from body weight gain and glucose intolerance induced by HFD whereas energy intake was higher in transgenic mice suggesting larger energy expenditure." (PMID 23741455, 2013). "All HFD‐treated mice became obese, but only WT and TLR4 KO mice developed glucose intolerance." (PMID 31044181, 2019). "Finally, it is possible that the upregulated expression of TLR4 on transferred db/db-derived Ly6Chigh monocytes may have exacerbated glucose intolerance." (PMID 32097444, 2020). "Consequently, it is more likely that low-grade inflammation causing glucose intolerance is correlated to Gram-negative bacteria and subsequent LPS and TLR4 stimulation rather than to Gram-positive bacteria and subsequent TLR2 stimulation." (PMID 24369539, 2013). "On the other hand, WT exposed to 1,2-NQ displayed higher fasting blood glucose and glucose intolerance, but the TNFR1 and TLR4 knockout mice remained protected from these effects." (PMID 37383489, 2023). "The main finding of this study was that, prolonged (24 h) exposure of IL-6 mediates TLR4 gene expression via STAT3-SOCS3 activation and induces glucose intolerance and inflammation in the skeletal muscle." (PMID 28706484, 2017). "WT mice fed with HFD developed glucose intolerance as demonstrated by a higher AUC (45%, P = 0.01), whereas no significant change was observed in TLR4−/− mice." (PMID 23741455, 2013). "Therefore, the absence of TNFR1 and TLR4 partially protects from 1,2-NQ-induced glucose intolerance." (PMID 37383489, 2023).
schizophrenia (27 papers, 2016 to 2025). A major psychotic disorder characterized by abnormalities in the perception or expression of reality. "Postmortem results show increased TLR4 protein expression in the prefrontal cortex of schizophrenia patients, which is associated with activation of the MyD88 and NF-κB pathways." (PMID 41346597, 2025). "Our findings support altered TLR4 signaling pathway activity in association with deficits in cognition and white matter integrity in schizophrenia." (PMID 36051545, 2022). "The exception is the microglial-associated transcript TLR4, which is unchanged in high inflammation schizophrenia despite robust (approximately twofold) increases in high inflammation controls." (PMID 34650030, 2021). "Given that SZ patients also experience loss of gut microbiota homeostasis, targeting the TLR4 signaling pathway and focusing on bacterial translocation and microbiota may offer new avenues for immunomodulatory therapy in schizophrenia." (PMID 41346597, 2025). "Polymorphisms in the TLR4 gene have also been linked to increased susceptibility to schizophrenia." (PMID 40153412, 2025). "Future studies should also account for potential confounding factors affecting the association between TLR4 and schizophrenia, such as TLR4 gene polymorphisms, AP medication type, duration and dosage, duration of disease, and different phases of schizophrenia (prodromal, active, residual)." (PMID 40153412, 2025). "Further, genetic polymorphisms of TLR4 have been associated with schizophrenia in several studies." (PMID 37511534, 2023). "We hypothesized that peripheral inflammation in this ‘high inflammation’ patient subgroup may be linked to schizophrenia-specific overexpression of transcripts that activate NF-κB, including TLR4, in leukocytes." (PMID 35027554, 2022). "Three SNPs, rs955302 (β^G×ε4*=4.0,p=0.01), rs4837254 (β^G×ε4*=2.3,p=0.04) and rs12342331 (β^G×ε4*=2.1,p=0.04), are located at the intergenic region between ASTN2 and TLR4 at Chromosome 9 and are 400k, 430k, and 492k downstream of rs1360695 associated with Schizophrenia." (PMID 30133451, 2018). "Impaired TLR4 signal pathways may result in a decreased capability of the body recognizing and clearing invading pathogens in vivo, causing sustained mild infection in schizophrenia." (PMID 36051545, 2022). "First, there are few articles on this topic to date, making it difficult to establish a definitive relationship between TLR4 and schizophrenia." (PMID 40153412, 2025). "Recent research has identified the TLR4/MyD88/NF-κB pathway as playing a central role in various neurological disease models, suggesting its relevance in schizophrenia pathogenesis." (PMID 41346597, 2025). "Five studies (518 individuals; 276 persons with schizophrenia and 242 HCs) assessed the basal percentage of TLR4+ monocytes." (PMID 40153412, 2025). "Eleven studies (889 individuals; 473 persons with schizophrenia and 416 HCs) dealing with basal TLR4 expression were assessed." (PMID 40153412, 2025). "To date, few studies have addressed the relationship between neuroimaging markers and TLR4 expression in patients with schizophrenia." (PMID 40153412, 2025). "According to qualitative data synthesis, persons with schizophrenia exhibit blunted monocytic TLR4 activation after stimulation." (PMID 40153412, 2025). "Four studies (439 individuals; 239 persons with schizophrenia and 200 HCs) evaluated the TLR4 expression pattern after stimulation." (PMID 40153412, 2025). "Three studies focused on TLR4 gene/mRNA expression in PBMCs, with two comparing outcomes between persons with schizophrenia on APs and HCs and one assessing both drug-naïve and AP-medicated individuals." (PMID 40153412, 2025). "Studies attributed to TLR4 expression after stimulation suggested weakened monocytic activation in individuals with schizophrenia." (PMID 40153412, 2025).
schizophrenia (continued). "Four of the eleven studies (439 individuals; 239 persons with schizophrenia and 200 HCs) also investigated stimulated TLR4 expression after activation by its ligand(s)." (PMID 40153412, 2025). "TLR4 gene expression was evaluated in two studies (101 individuals; 51 persons with schizophrenia and 50 HCs)." (PMID 40153412, 2025). "The results of meta-analyses suggested a trend toward higher basal monocytic TLR4 density in persons with schizophrenia than in HCs." (PMID 40153412, 2025). "One study revealed upregulated TLR4 gene expression in drug-naïve persons with schizophrenia compared to HCs." (PMID 40153412, 2025). "Recent studies have suggested a diminished monocytic TLR4 response to LPS stimulation in individuals with schizophrenia, with increased TLR4 expression as a compensatory mechanism for this attenuated monocytic activation." (PMID 40153412, 2025). "Consistently, TLR4-induced mild inflammation has been observed in both first-episode and chronic schizophrenia patients." (PMID 40153412, 2025). "Our study reveals that LY96 expression is significantly elevated in schizophrenia patients compared to control samples, thereby supporting the involvement of LY96 in LPS-induced TLR4 signaling pathway activation and the pathogenesis of schizophrenia." (PMID 40242178, 2025). "TLR4 mRNA expression was examined in one study (56 individuals), which suggested that TLR4 expression was downregulated in persons with schizophrenia compared with HCs." (PMID 40153412, 2025). "In AP-free settings, all studies, except one, reported increased monocytic TLR4 expression in persons with schizophrenia compared to HCs." (PMID 40153412, 2025). "Later investigations yielded varying results, with some reporting nonsignificant results and others reporting increased monocytic TLR4 density in individuals with schizophrenia." (PMID 40153412, 2025). "Postmortem studies have further revealed altered TLR4 expression and signaling in the brains of individuals with schizophrenia." (PMID 40153412, 2025). "Only a few studies have sought to address the gap in understanding the impact of APs on TLR4 expression in persons with schizophrenia." (PMID 40153412, 2025). "This systematic review included 11 studies (473 persons with schizophrenia and 416 HCs) investigating basal TLR4 expression and 4 studies (239 persons with schizophrenia and 200 HCs) investigating stimulated TLR4 expression in individuals with schizophrenia." (PMID 40153412, 2025). "Disparities exist regarding the relationship between TLR4 and the clinical or cognitive features of people with schizophrenia." (PMID 40153412, 2025). "On the other hand, studies reported that antipsychotic-treated patients showed higher expression of tlr4 mRNA and myd88 mRNA in peripheral blood and postmortem brain tissue samples, respectively, over antipsychotic-free patients (schizophrenia)." (PMID 37627253, 2023). "TLR4 polymorphism also showed an association with schizophrenia risk; four SNPs of TLR4 were investigated, of which three (rs11536889-3′UTR, rs1927911-intron, and rs1927914-5′UTR) showed an association with schizophrenia." (PMID 37627253, 2023). "TLR4 expression in peripheral blood cells is significantly higher in drug-naïve schizophrenia patients than in controls." (PMID 37511534, 2023). "Within the prefrontal cortex of patients with schizophrenia, the gene expression of the Toll-like receptors 4 (TLR4), pivotal in the proinflammatory pathway, is altered." (PMID 37371435, 2023). "In family 1, with singleton schizophrenia, we detected four rare variants in genes implicated in schizophrenia, including p.Arg1627Trp of LAMA2, p.Pro1338Ser of CSMD1, p.Arg691Gly of TLR4, and Arg182X of AGTR2." (PMID 37511534, 2023). "Conversely, peripheral monocytes/macrophages appear to be overactive in some people with schizophrenia, evidenced by elevated blood levels of proinflammatory, macrophage-derived cytokines, and reported increases in TLR4 mRNA in patient leukocytes." (PMID 35027554, 2022).
schizophrenia (continued). "The current study also indicated an impaired TLR4 signaling pathway activation after LPS challenge, as manifested in lower TLR4 elevation in schizophrenia, consistent with previous reports." (PMID 36051545, 2022). "Partial correlations revealed that basal TLR4 levels significantly negatively correlated with whole-brain average FA (r = −0.405, p = 0.016) in patients with schizophrenia." (PMID 36051545, 2022). "Some studies have demonstrated that antipsychotics can affect TLR4 levels and cognitive function in patients with schizophrenia." (PMID 36051545, 2022). "We found that elevations in TLR4 and RelB appear more related to inflammatory status than to a diagnosis of schizophrenia, but changes in TNFR2 occur in both the high and low inflammation patients (but were exaggerated in high inflammation patients)." (PMID 35027554, 2022). "But the role of TLR4 signaling in cognitive function between first-episode and chronic schizophrenia is inconsistent, presenting a context-dependent pattern." (PMID 36051545, 2022). "Intriguingly, an increase in IFN-γ—as we report here—primes macrophages for stimulus-induced secretion of pro-inflammatory cytokines via enhancement of TLR4 signaling, further supporting that people with schizophrenia are positioned to over-respond via TLR4." (PMID 35027554, 2022). "Overall, TLR4 up-regulation in patient circulating leukocytes plausibly contributes to increased peripheral inflammation in a subset of people with schizophrenia." (PMID 35027554, 2022). "We also attempted to explore the relationship between TLR4 levels and psychopathology in patients with schizophrenia." (PMID 36051545, 2022). "In conclusion, the current study showed that TLR4/NF-κB/IL-1β signaling elevates in activity but responds sluggishly to LPS stimulation in schizophrenia." (PMID 36051545, 2022). "Although suicide was the cause of death for an important number of MDD subjects in the present study, opposite results for TLR-4 and NF-κB expression have been recently described in a schizophrenia population mainly dead by suicide." (PMID 30180869, 2018). "Studies addressing basal TLR4 expression in persons with schizophrenia and healthy controls." (PMID 40153412, 2025). "Studies addressing stimulated TLR4 expression in persons with schizophrenia and healthy controls." (PMID 40153412, 2025). "Recognizing these issues, along with the potential role of TLR4 as a novel therapeutic target, we conducted a systematic review and meta-analysis of the literature on the basal expression and activation of TLR4 in peripheral blood mononuclear cells (PBMCs) in individuals with schizophrenia." (PMID 40153412, 2025). "Alterations in the microbial flora, gut inflammation, increased intestinal barrier permeability (forming a “leaky gut”), bacterial translocation, and exposure to stressful environments in schizophrenia, may trigger innate immunity via TLR4 stimulation." (PMID 41346597, 2025). "The aim was to summarize existing literature, identify knowledge gaps, and focus on the dysregulated immune response, particularly involving TLR4, which may significantly contribute to the pathophysiology of schizophrenia." (PMID 40153412, 2025). "This study revealed a trend towards elevated monocytic TLR4 density alongside diminished monocytic TLR4 activation in individuals with schizophrenia, indicating a dysregulated immune response that may play a crucial role in the pathophysiology of the disorder." (PMID 40153412, 2025). "Notably, increased TLR4 expression, myeloid differentiation primary response gene 88 (MyD88), and NF-кβ, which are components of the TLR4 signaling pathway, were detected in the prefrontal cortex of people with schizophrenia." (PMID 40153412, 2025). "However, excluding one study indicated significantly greater TLR4 gene expression in persons with schizophrenia than in HCs." (PMID 40153412, 2025).
schizophrenia (continued). "This may suggest that chronic subtle inflammation mediated by basal TLR4 can diminish cognitive function, while a rapid immune response mediated by stimulated TLR4 might benefit cognitive function in people with schizophrenia." (PMID 40153412, 2025). "Additionally, identifying the differences between acute and chronic activation of TLR4 in schizophrenia patients is crucial for obtaining a comprehensive understanding of this disease." (PMID 40153412, 2025). "At the same time, while TLR4 might be overexpressed in persons with schizophrenia, its stimulation might induce a weaker increase in TLR4 expression and reduced proinflammatory cytokine production compared to healthy controls (HCs)." (PMID 40153412, 2025). "Altered TLR4 expression and function may contribute to schizophrenia by affecting the innate immune system activation, neuroinflammation, increased susceptibility to infection, and structural brain changes." (PMID 40153412, 2025). "However, they observed a smaller increase in TLR4 expression in persons with schizophrenia than in HCs after stimulation using the following formula: (unstimulated MFI/stimulated MFI)." (PMID 40153412, 2025). "The second section included five studies pooling data on the basal percentage of TLR4+ monocytes, and the third section included combined results from two studies comparing basal TLR4 gene expression between persons with schizophrenia and HCs." (PMID 40153412, 2025). "In recent years, studies on SZ bodily fluids have consistently reported increased numbers of TLR4-positive monocytes and elevated TLR4 expression in the peripheral blood of schizophrenia patients, suggesting that TLR4 upregulation is a key factor in the immunopathological process of schizophrenia." (PMID 41346597, 2025). "Drug-naïve patients with schizophrenia exhibited increased TLR4 mRNA levels and unaltered TLR3 mRNA levels in peripheral blood mononuclear cells (PBMC), alongside elevated TLR4 and TLR8 mRNA levels and reduced TLR3 mRNA levels in white blood cells compared to healthy controls." (PMID 38792602, 2024). "Increased TLR4-mediated immune responses have been observed in patients with schizophrenia." (PMID 37511534, 2023). "Human postmortem studies carried out on individuals diagnosed with schizophrenia, brain samples showed lower tlr4 mRNA and protein levels, and downregulation of il6, il10, and tnfa mRNA in the prefrontal cortex (PFC) region, and elevated TLR4 protein levels in the cerebellum region." (PMID 37627253, 2023). "Notably, monocytic TLR4 expression was significantly correlated with the decreases in white matter FA in schizophrenia, inter-linking white matter deficits with impairment in oligodendrocyte function and axonal myelination." (PMID 36051545, 2022). "Together with previous findings that TLR4 activation in patient immune cells leads to exaggerated pro-inflammatory cytokine release, higher TLR4 mRNA in white blood cells would be consistent with a higher number of TLR4 receptors at the cell surface in schizophrenia." (PMID 35027554, 2022). "We examined the correlation between cognitive performance and white matter FA, aiming to confirm the hypothesis that TLR4-mediated inflammation may indirectly affect cognitive function by influencing white matter integrity in schizophrenia." (PMID 36051545, 2022). "Our findings showed that the TLR4 pathway was activated in stable chronic schizophrenia." (PMID 36051545, 2022). "The TLR4 signaling pathway may have a dual effect on cognitive function in schizophrenia, manifesting as both benefiting cognitive function and impairing cognitive performance." (PMID 36051545, 2022). "That people with schizophrenia have increased leukocyte transcription of the receptor TLR4 that activates NF-κB is supported by the current findings, and even patients with low inflammation had significantly higher TLR4 mRNA than controls with low inflammation." (PMID 35027554, 2022).